MTOR (mechanistic target of rapamycin kinase)
Diseases named in the same sentence as MTOR in open-access papers (continued):
Sharing a sentence is not in itself a finding about the gene and the disease.
breast cancer (continued). "Lastly, we demonstrated that simultaneous inhibition of GLS and mTOR is synergistic in responder lines signifying a novel combination approach for the development of GLS inhibitors in basal-type breast cancers." (PMID 28950000, 2017). "Autophagy was observed to promote apoptosis via the Akt/mTOR signaling pathway in breast cancer cell lines during the combined treatment." (PMID 29100392, 2017). "Xuaet al. reported that miRNAs are involved in the regulation of chemoresistance to ovarian cancer, colorectal cancer, non‐small cell lung cancer or breast cancer by targeting mTOR/P70S6K1 and MAP/ERK kinase kinase 1 (MEKK1), among others." (PMID 28411377, 2017). "The present meta-analysis, which included nine articles and 3051 participants, assessed the significance of p-mTOR expression in breast cancer." (PMID 28114374, 2017). "FGFR1 TKI induces protective autophagy through suppressing AKT/mTOR signaling pathway in FGFR1-amplified breast cancer cell lines." (PMID 28558758, 2017). "Overall, our data demonstrate a new mechanism of an independent regulation of SK1 and VEGF by mTOR in hormone-insensitive prostate and breast cancers." (PMID 28615679, 2017). "Knockdown of IGF-IR or inhibition of its downstream pathway, PI3K/Akt/mTOR, can reduce the breast cancer stem cells populations and suppress EMT process in breast cancer cells." (PMID 28137302, 2017). "It has been shown that PI3K/mTOR signaling is upregulated in trastuzumab-resistant breast cancer cells, and blockade of this pathway restores sensitivity toward trastuzumab." (PMID 29296217, 2017). "Previous studies have identified that PI3K/AKT/mTOR signaling plays an irreplaceable role in the progression and maintenance of breast cancer." (PMID 29228721, 2017). "The mammalian target of rapamycin (mTOR) inhibitor everolimus has been approved in combination with exemestane for treatment of hormone receptor-positive HER2-negative (HR + HER-) advanced breast cancer after failure of treatment with letrozole or anastrozole." (PMID 28878375, 2017). "The PI3K/Akt/mTOR signaling pathway is a potentially high relevance to all three major subtypes of breast cancer, driving cell proliferation, growth, and survival." (PMID 29156828, 2017). "The AKT/mTOR pathway is critical for control of cell survival and differentiation in various cell types, such as endothelial cells, human breast cancer epithelial cells, and smooth muscle cells." (PMID 28098802, 2017). "Deregulation and activation of the phosphoinositide 3-kinase (PI3K)/Akt/mammalian (or mechanistic) target of rapamycin (mTOR) pathway have a major role in proliferation and cell survival in breast cancer." (PMID 28991258, 2017). "We previously reported that Rac inhibition suppresses both the MEK/ERK and PI3K/AKT/mTOR pathways in ER+ breast cancer cells." (PMID 28423521, 2017). "The signaling pathway involving PI3K, the Akt serine/threonine specific protein and the mammalian target of rapamycin (mTOR) is frequently deregulated in human breast cancers." (PMID 27935867, 2017). "In terms of ErbB2 downstream effectors, mTOR inhibitor, everolimus, is approved in many countries for advanced hormone receptor‐positive, ErbB2‐negative breast cancer in combination with exemestane." (PMID 28781955, 2017). "For instance, dual inhibitors of the PI3K/mTOR pathway have been found to be more efficient at inhibiting the proliferation of breast cancer cells than specific inhibitors of PI3K or mTOR." (PMID 28056771, 2017). "The PI3K/Akt/mTOR pathway is another pivotal and frequently altered signalling pathway in human breast cancer." (PMID 27923036, 2017). "Further, mammalian target of rapamycin (mTOR) inhibition, mediated by metformin, sensitized breast cancer cell lines and thyroid cancer cells to cytotoxic effect of everolimus and vemurafenib, respectively." (PMID 28698800, 2017).
breast cancer (continued). "First, it is the first meta-analysis assessing the clinical and prognostic role of p-mTOR expression in breast carcinoma." (PMID 28114374, 2017). "One article assessed the prognostic value of p-mTOR (DFS) in breast carcinoma by the Kaplan-Meier method." (PMID 28114374, 2017). "mTOR inhibitors such as everolimus, which are targeted drugs in breast carcinoma, have been extensively tested in clinical trials for breast carcinoma." (PMID 28114374, 2017). "Eight studies provided integrated original information of the relationship between p-mTOR expression and clinical pathological parameters in breast carcinoma directly." (PMID 28114374, 2017). "The aim of the present study was to assess the relationship between p-mTOR expression and prognosis in breast carcinoma based on a systematic review and meta-analysis." (PMID 28114374, 2017). "Aberrant activation of the PI3K/Akt/mTOR signaling pathway is involved in oncogenesis and disease progression in breast carcinoma." (PMID 28114374, 2017). "In consideration that the PI3K/Akt/mTOR signaling participates in the regulation of cyclin D and this pathway is activated in most breast tumors, the combination of ribociclib and PI3K/mTOR inhibitor alpelisib (BYL719) was investigated in breast carcinoma." (PMID 28438180, 2017). "Everolimus successfully targets the Akt/mTOR pathway in AI-sensitive and AI-resistant breast cancer cells." (PMID 27421652, 2016). "Quercetin at 15 μM in vitro and 15 mg/kg in vivo, inhibits Akt/mTOR signalling, induces cell cycle arrest, and inhibits breast cancer growth and metastasis." (PMID 27999314, 2016). "We show that metformin treatment in MCF‐7 breast cancer cells induced degradation of mTOR and sequestration of this protein in a perinuclear region." (PMID 27748082, 2016). "The activity of dasatinib in inhibiting SRC family members, activating an intracellular signaling that converges on mTOR pathway, has been demonstrated in breast cancer models." (PMID 27391433, 2016). "A significant inverse correlation was found between miR-100 and mTOR in invasive breast cancers, implicating mTOR as a target of miR-100 in breast cancer." (PMID 26744318, 2016). "In HER2-mutant breast cancer, mutational activation of the PI3K/AKT/mTOR pathway is among the most frequent mechanisms contributing to both the intrinsic and acquired therapy resistances." (PMID 27015560, 2016). "Its use in vitro and in vivo, to block tumor cell growth and relapse, displayed biological effects superior to those elicited by mTOR inhibitors, at least in the context of breast cancer." (PMID 27155197, 2016). "This suggests a different B7-H3-mediated mechanism of API-2 and everolimus on breast cancer cell sensitivity downstream of mTOR." (PMID 26771843, 2016). "Our expression analysis in human breast cancer tissues and cell lines, including cell lines where miR-100 expression was manipulated, further confirmed mTOR as a target of miR-100." (PMID 26744318, 2016). "The results demonstrated combined RQC and gefitinib was more efficient than either treatment alone at inhibiting mammary cancer growth and metastasis via inhibition of Akt signaling and mTOR." (PMID 27999314, 2016). "The completion of three recent clinical trials, two of which specifically examined MK-0646 and MK-8669, reinforce the added value of targeting IGF-1R in conjunction with mTOR in advanced hormone receptor-positive breast cancer tumors." (PMID 27765027, 2016). "Previous study reported that wedelolactone inhibited Akt/mTOR signaling in breast cancer-induced osteoclastogenesis." (PMID 27558652, 2016). "Use of metformin in MCF-7 breast cancer cells exhibited reduction in phosphorylation of S6 kinase, ribosomal protein S6 and eIF4E binding protein, along with inhibition of mTOR and reduced translation initiation due to AMPK activation." (PMID 27004404, 2016). "There is limited data on co-expression of FGFR/FGR amplifications and PI3K/ AKT/mTOR alterations in breast cancer." (PMID 27489863, 2016).
breast cancer (continued). "This study demonstrated the efficacy of AI with mTOR inhibitor, suggesting that concurrent treatment with multiple drugs including AI was hopeful for AI-resistant breast cancer." (PMID 27228187, 2016). "The observation that re-expression of ERRα in lapatinib-resistant cells depends on mTOR reactivation also denotes an important role of ERRα in breast cancer biology." (PMID 27402251, 2016). "Together, our data suggest that total mTOR protein level is high in breast cancer cells, particularly in the MCF‐7 cells, which correlates with mTOR activity in these cells." (PMID 27748082, 2016). "In an earlier publication, we provided evidence that CCL5 treatment promotes the proliferation of MCF-7 human breast cancer cells, through mTOR-dependent mRNA translation of a subset of proteins associated with cell cycle progression and survival." (PMID 27335323, 2016). "In estrogen receptor positive breast cancer, long term treatment with antiestrogen therapy resulted in up-regulation of mTOR signaling via the PI3K/AKT axis." (PMID 27826244, 2016). "Mechanistically, targeting mTOR appeared to mediate miR-100's function in sensitizing breast cancer cells to paclitaxel, but other mechanisms also seem to be involved, including targeting other molecules such as PLK1." (PMID 26744318, 2016). "The relationship of mTOR-targeted efficacy with oncogenic dysregulation of mTOR signaling was further studied in a panel of breast cancer lines." (PMID 27563814, 2016). "Metformin has been found to decrease HER2 expression in human breast cancer cells by directly inhibiting p70S6K1, which is a downstream effector of mTOR." (PMID 27004404, 2016). "The interaction between PI3K/AKT/mTOR signaling and ER signaling has been found in breast cancer cells." (PMID 26795955, 2016). "Collectively, these results reveal an essential role for mTOR in de novo lipogenic process particularly in HER2/PIK3CA-hyperactive breast cancer cells like MDA-MB-453." (PMID 27563814, 2016). "PI3K/mTOR is a common downstream pathway of growth factor receptors, which is often upregulated in endocrine-resistant breast cancer and proven clinically as a novel treatment target." (PMID 27659519, 2016). "In breast cancer, resistance to endocrine therapy is mediated through mTOR-induced phosphorylation of estrogen receptors and the addition of everolimus disrupts this phosphorylation and resulting resistance." (PMID 27501793, 2016). "Treatment of breast cancer cells with metformin and rapamycin, two known mTOR inhibitors, resulted in a significant decrease in the total level of mTOR protein in MCF‐7 cells." (PMID 27748082, 2016). "To date, everolimus, an orally available mTOR inhibitor approved for the treatment of advanced breast cancer, neuroendocrine tumors of pancreatic origin, and advanced renal cell carcinoma, has met multiple clinical needs in oncology." (PMID 27223077, 2016). "Additional experiments further confirmed that mTOR is indeed a target of miR-100 in breast cancer cells." (PMID 26744318, 2016). "The potential prognostic value of mTOR and phosphorylated mTOR (p-mTOR) has also been extensively studied in a variety of cancers, including lung cancer, gastric cancer, breast cancer, colorectal cancer and urological cancer." (PMID 27835987, 2016). "Recently, reduced NAD+/NADH ratios were shown to drive the metastatic progression of MDA-MB-435 and MDA-MB-231 breast cancer xenografts by activating AKT/mTOR and autophagy signaling pathways while increasing the NAD+/NADH ratio inhibited tumor growth." (PMID 26725848, 2016). "In summary, we report the synthesis and biological evaluation of imidazoles that induce apoptosis in breast cancer cells by negatively regulating PI3K/Akt/mTOR signaling pathway." (PMID 27097161, 2016). "By comparing molecules involved in both groups, we found that mTOR was the only known miR-100 target that has also been shown to affect breast cancer sensitivity to paclitaxel." (PMID 26744318, 2016).
breast cancer (continued). "mTOR inhibition exhibited promising antitumor effects in breast cancer; however, its effect is compromised by several feedback mechanisms." (PMID 27748082, 2016). "Participation of FZD9 in carcinogenesis has been reported in various cancers, indicating their potential roles in breast cancer, such as mTOR signaling pathway." (PMID 27786176, 2016). "Recent data reported that dual Src and mTOR inhibition was highly effective in two mouse models of breast cancer." (PMID 27155197, 2016). "Quercetin, one of the natural polyphenols, in combination with resveratrol and catechin (RQC), has been reported to inhibit the PI3K/Akt/mTOR signaling pathway and breast cancer progression in vitro and in vivo." (PMID 27999314, 2016). "A better understanding of this complex systems network will be critical to optimize response to anti-growth factor receptor and signaling intermediate (e.g. PI3K, mTOR) inhibitors in breast cancer." (PMID 27765041, 2016). "Randomized phase 3 clinical trials have confirmed the therapeutic effects of everolimus, an mTOR inhibitor, in breast cancer patients." (PMID 27487140, 2016). "For breast cancers, most of the alterations actionable with an approved drug were in the PTEN/PI3K/mTOR axis (with several mTor inhibitors approved, including everolimus, which is on-label for breast cancer) or in the HER pathway." (PMID 26848768, 2016). "Although the addition of the oral mTOR inhibitor everolimus to endocrine therapy improves progression-free survival in breast cancer, temsirolimus showed limited activity." (PMID 26686201, 2016). "AE suppressed YB-1 expression through the downregulation of ILK/Akt/mTOR-regulated Twist expression in HER-2-overexpressing breast cancer cells." (PMID 27391337, 2016). "Our study demonstrates that the IGF1R/p110β/AKT/mTOR axis confers resistance to BYL719 in PIK3CA mutant breast cancers." (PMID 27048245, 2016). "To examine the impact of metformin‐induced mTOR degradation on the phenotype of breast cancer cells, we compared the effect of various mTOR inhibitors on the proliferation and migration potentials of different breast cells." (PMID 27748082, 2016). "To investigate the possibility of reduced degradation of mTOR protein in the breast cancer cells, we compared the stability of mTOR protein using CHX) treatment and immunoblotted for mTOR protein." (PMID 27748082, 2016). "The mTOR inhibitor everolimus has been recently approved for the treatment of advanced ER+ breast cancer, and several trials are currently evaluating the efficacy of mTOR inhibitors in the TNBC subtype." (PMID 27374081, 2016). "CIP caused the accumulation of breast cancer cells in Sub-G1 phase, increased the executioner caspase-3/7 activity, downregulated the phosphorylation of PDK, Akt and mTOR in breast cancer cells." (PMID 27097161, 2016). "This study provides additional insight into the mechanism(s) of action of everolimus that can be used to enhance the utility of mTOR inhibitors as part of combination therapy for AI-resistant breast cancer." (PMID 27421652, 2016). "We sought to investigate novel role of mTOR in glucose to lipid metabolism in breast cancer, particularly those governed by mTORC2, a key component of HER2, PI3K pathway and is resistant to rapalog therapy." (PMID 27015560, 2016). "The findings of this work emphasized results of previous research about beneficial role of mTOR inhibition in breast cancer." (PMID 27748082, 2016). "Oleocanthal treatment (10 μM) caused a marked downregulation of the phosphorylated mTOR (p-mTOR) in a metastatic breast cancer cell line (MDA-MB-231), suggesting that the anti-carcinogenic activity of oleocanthal is potentially mediated by mTOR inhibition." (PMID 27999296, 2016). "In breast cancer, the PI3K/Ak/mTOR pathway is important in the clinical sensitivity of breast cancer to endocrine therapy." (PMID 27174543, 2016).
breast cancer (continued). "Despite the established role of mTOR activation in breast cancer, the status of total mTOR protein and its impact on the tumor behavior and response to treatment are poorly understood." (PMID 27748082, 2016). "It was reported that HuR is activated through the PI3K/AKT/NF-κB pathway in gastric cancers and through the mTOR/HSF1 pathway in breast cancer cells." (PMID 27166258, 2016). "Here we report that lapatinib induces the degradation of the nuclear receptor ERRα, a master regulator of cellular metabolism, and that the expression of ERRα is restored in lapatinib-resistant breast cancer cells through reactivation of mTOR signalling." (PMID 27402251, 2016). "The mTOR inhibitor everolimus was combined with an aromatase inhibitor exemestane in breast cancer patients who progressed while receiving an aromatase inhibitor." (PMID 27501793, 2016). "This study showed an evidence that metformin and rapamycin resulted in a decrease in the overall level of mTOR protein in MCF‐7 breast cancer cells in addition to the inhibition of mTOR activation." (PMID 27748082, 2016). "For instance, plumbagin induced autophagic cell death in breast cancer via the AKT/mTOR signaling pathway." (PMID 26999089, 2016). "Convergence of c-Myc and PI3K/mTOR pathway is also becoming evident in hematopoietic malignancies and breast cancer." (PMID 26536665, 2016). "In fact, the mTOR inhibitors everolimus and temsirolimus have been approved for the treatment of renal cancer and breast cancer." (PMID 26657290, 2016). "The activation of the PI3K/Akt/mTOR pathway is considered clinically relevant for tumor escape from hormone dependence in breast cancer, promoting the survival of breast cancer cells in estrogen-deprived conditions." (PMID 27421652, 2016). "Clearly, mislocalisation of Scrib in a murine model of breast cancer has potent oncogenic activity that appears to be related to the control of mTOR signalling, and this also occurs in HPV-positive cells." (PMID 27483446, 2016). "Expression evaluation, functional and molecular tests, and bioinformatic and survival analyses suggest that miR-100 plays a role in breast cancer development by promoting paclitaxel sensitivity in part by targeting mTOR." (PMID 26744318, 2016). "Rapamycin is the mTOR inhibitor, which previously showed overcoming endocrine resistance in breast cancer cells." (PMID 27196739, 2016). "Prolonged treatment of human pancreatic cancer cell lines MiaPaCa-2, PANC1 and BON, and the breast cancer cell line MCF-7 with mTOR inhibitors resulted in an increase in 4E-BP3 protein levels." (PMID 27319316, 2016). "Genetic alterations in the phosphatidylinositol 3-kinase (PI3K)/V-AKT murine thymoma viral oncogene homolog (AKT)/mechanistic target of rapamycin (MTOR) pathway are common events in breast cancer." (PMID 27576528, 2016). "mTOR inhibition of aromatase inhibitor (AI)-resistant breast cancer is currently under evaluation in the clinic." (PMID 27421652, 2016). "Recent data in breast cancer cells have shown that BYL719 resistance was conferred by IGF1R/p110β/Akt/mTOR activation." (PMID 27602501, 2016). "Our results revealed that MFB activated AMPK and inhibited mTOR with significantly greater potencies than metformin in all of the tested breast cancer cell lines." (PMID 27223262, 2016). "As a result, recent clinical trials have focused instead on simultaneous targeting of the PI3K/AKT/mTOR and ER pathways in ER+ breast cancer." (PMID 27421652, 2016). "The relatively safe profile of metformin makes it a promising agent for mTOR inhibition in breast cancer, particularly that mTOR inhibitors are usually required in high doses to achieve better antitumor effects." (PMID 27748082, 2016). "In a first series of experiments, we examined the effects of CCL5 on activation of the AKT/mTOR pathway in MDA-MB-231 human breast cancer cells." (PMID 27335323, 2016).